AR (androgen receptor)
Diseases named in the same sentence as AR in open-access papers (continued):
Sharing a sentence is not in itself a finding about the gene and the disease.
prostate carcinoma (continued). "Although, AR is an essential player that controls different elements in all phases of prostate carcinogenesis, but many other signaling pathways along with their interactions with AR signaling, are also critically implicated especially in advanced stages of prostate cancer." (PMID 31136301, 2019). "Here we show, for the first time, that intermittent androgen deprivation and loss of AR signalling may promote the existence of “hybrid” prostate cancer cells that retain both NE-like and epithelial qualities, most notably persistent nuclear localisation of hASH1." (PMID 31836808, 2019). "To test if loss of E-cadherin can modulate AR mediated transcription via altered β-catenin levels in prostate cancer cells, we specifically knocked down endogenous E-cadherin expression using small hair-pin RNA interference approaches in human prostate cancer cell lines." (PMID 31658259, 2019). "Data from ongoing clinical trials will help to address the questions on whether we can apply PARPi beyond BRCA1/2-mutated prostate cancer; whether combining PARPi with either AR signaling inhibitors or checkpoint inhibitors will work better in HRR-deficient mCRPC than HRR-intact mCRPC." (PMID 31404966, 2019). "AR in healthy prostate epithelium tissue regularly controls cell proliferation and programmed cell death; however, the loss of this control mechanism is observed in prostate cancer cells, and the molecular mechanisms remain unclear." (PMID 31395805, 2019). "Although AR is the classical target for prostate cancer prevention and treatment, several recent studies indicated that estrogen and estrogen receptor (ER) have also been implicated in prostate cancer development, prostate cancer cell stemness, and tumor progression." (PMID 30987073, 2019). "In 2015, as part of the Prostate Cancer Foundation–Movember Foundation Reproducibility Initiative, we published a Registered Report that described how we intended to replicate selected experiments from the paper “Androgen Receptor Splice Variants Determine Taxane Sensitivity in Prostate Cancer”." (PMID 29682426, 2018). "However, when circulating concentrations are very low, reduced androgen receptor signalling may lead to a reduction in prostate cancer risk." (PMID 30077399, 2018). "The expression of AR in stromal fibroblasts is required for the development and maintenance of the normal prostate, and for the development of prostate cancer, yet interestingly stromal AR expression is frequently reduced in prostate cancer where it is associated with poor clinical outcomes." (PMID 29721186, 2018). "A potential difficulty of comparing androgen signaling across prostate cancer cells is - depending on the line - the AR is mutated, alternatively spliced, and expressed at different levels, all of which could affect the transcriptional output measured in response to androgen." (PMID 30305041, 2018). "Our findings related to the HSP70/STUB1/AR-V7 complex are important as this mechanism may represent a general chaperone–ubiquitin–proteasome mechanism for the regulation of AR variants protein stability that may involve in treatment resistance in advanced prostate cancer." (PMID 30446660, 2018). "Genomic rearrangements including intron sequences also occur in situ within prostate cancers expressing AR mRNA splice variants, although the major factor leading to the expression of AR splice variants is the corresponding increased expression levels of the full-length AR isoform." (PMID 28382513, 2017). "Also, AR transcriptional activity is increased in SPOP mutated prostate cancer." (PMID 29262542, 2017). "Additionally, responses to AR inhibitors in prostate cancers with PTEN loss may depend on the level of PI3K pathway activation." (PMID 28420128, 2017). "However, due to increased protein levels of AR or AR mutations that cause AR-resistance to anti-androgen treatment, patients may relapse, with the development of a castration-therapy-resistant stage of prostate cancer." (PMID 28212551, 2017).
prostate carcinoma (continued). "Furthermore, our data show that warfarin inhibits PPARγ and AR signaling, which suggests that inhibition of these pathways could be used to reduce the risk of developing prostate cancer." (PMID 28099154, 2017). "Also AR-positive prostate cancers with combined mutational aberrations in the AR as in the cell modell CRW22Rv1 may be resistant to ERβ-selective treatments with 8ß-VE2." (PMID 28380417, 2017). "Because inhibition of AR, as seen in the 5α-reductase studies, can reduce the risk of prostate cancer, we hypothesized that the reduced risk of prostate cancer associated with warfarin usage could be mediated, at least in part, by its inhibitory effects on AR signaling." (PMID 28099154, 2017). "However, it is possible that ligand-induced changes in expression of miRNAs that control the net amount of each receptor or its associated coregulators could influence the extent of AR-PPARγ interactions within normal prostate and prostate cancers." (PMID 29181019, 2017). "Therefore, understanding the physiological functions and the regulatory mechanisms responsible for the expression of AR target genes is absolutely critical for both elucidation of pathogenic mechanisms and the development of therapeutic strategies for prostate cancer." (PMID 27853318, 2016). "The prostate cancer cell lines that were chosen represent well-characterized tumor states (i.e., androgen dependent (LNCaP), androgen sensitive (LNCaP/C4-2) and castration resistant (22Rv1)), and also include examination of mutated forms of AR (i.e., LNCaP) and AR splice variants (i.e., 22Rv1)." (PMID 26918604, 2016). "Whether prostate cancer (PC) cells adapt to enzalutamide through alterations to AR directly (e.g. mutation or splice-variation), or whether there are distinct non-AR adaptive mechanisms of resistance is a fundamental question in understanding the development of enzalutamide resistance." (PMID 27036029, 2016). "Indeed, the androgen receptor variant 7 (AR-V7) provides a particularly important example of a PCa-specific isoform that is constitutively active and ligand-independent, contributing to castration resistance of prostate cancer cells." (PMID 27683107, 2016). "However, whether the resistance to cell death that is associated with this gene in prostate cancer is mediated by AR must be further elucidated." (PMID 26110379, 2015). "Additionally, expression levels of androgen receptor, which binds testosterone, may influence fertility in males and are associated with an increased risk of prostate cancer." (PMID 26056364, 2015). "Interestingly, IL-8 has also been implicated in elevating the transcriptional activity of the AR and may promote prostate cancer progression via an androgen independent pathway." (PMID 26305549, 2015). "However, further work is required to elucidate the functional difference between nuclear and cytoplasmic VAV3, which is reminiscent of the results for PAK1 and could be linked to the activation of the androgen receptor, as previously shown in prostate cancer." (PMID 24886537, 2014). "However, to assess the feasibility of niphatenone B for the treatment of advanced prostate cancer and prior to in vivo efficacy studies, more work was required to provide an indication of activity against constitutively active AR splice variants, specificity, and selection of the best enantiomer." (PMID 25268119, 2014). "Thus, loss of INPP4B in prostate cancers may cause increased IL-8 expression, activation of AR, and changes in the tumor microenvironment that lead to prostate cancer progression." (PMID 25248616, 2014). "Moreover, quercetin can affect the prostate cancer biology by inhibiting arachidonic acid metabolism through the blocking of phospholipase A2 and 5 as well as 12-lipooxygenase enzymes and inhibiting androgen receptor mutations." (PMID 24829522, 2014). "Moreover, AR expression has also been associated with PTEN expression in prostate cancer." (PMID 25608477, 2014).
prostate carcinoma (continued). "Additionally, some prostate cancers exhibit androgen resistance that may be due to transcriptional inactivation of the androgen receptor gene caused by DNA methylation." (PMID 25198391, 2014). "AR hypersensitivity, as a result of AR gene mutation and/or amplification, overexpression of coactivators, and AR cross-talking with other signal transduction pathways, often occurs and plays crucial roles in prostate cancer development, progression, and androgen-independent growth." (PMID 24573652, 2014). "In contrast, tumor hypoxia is progressively associated with increased AR activity, reduced oxidative defense, genomic instability, and apoptosis resistance, and it may be associated with the transition to androgen independence in prostate cancer." (PMID 23566222, 2013). "Therefore, AR gene amplification may play a direct role in prostate cancer progression and may be associated with failure of androgen deprivation therapy (ADT)." (PMID 24062990, 2013). "The diseases associated with later age at onset (i.e. prostate cancer, BC, osteoporosis) could still be significant contributors to AR CAGn distributions owing to the generally underappreciated capacity for negative selection at late-onset disease susceptibility alleles." (PMID 23467468, 2013). "Similarly, PolyGln tract of AR (encoded by AR_CAG) has been reported to be associated with susceptibility to a number of human diseases, such as prostate cancer, male infertility, cryptorchidism, hirsutism, Spinal and Bulbar Muscular Atrophy, and Kennedy’s disease, among others." (PMID 22792352, 2012). "Previous studies have demonstrated that polypeptide growth factor signal transduction pathways can stimulate AR activation, suggesting that the increase in growth factor and receptor expression could be causal in prostate cancer progression to castration resistance." (PMID 22761715, 2012). "One possibility is that prostate cancer cells achieve this by adapting their AR pathway to the low androgen/high antiandrogen levels, for example by mutation, amplification or truncation to a constitutively active AR, deregulation of AR cofactors and/or intratumoral androgen production." (PMID 21829708, 2011). "Several studies evaluating the expression of AR splice forms in a small number of prostate cancers suggest that AR variants are more readily detected in CRPC compared to hormone-naïve cancers, and may emerge due to the selective pressure of AR targeted therapy." (PMID 22114732, 2011). "The recent observation that high levels of cytoplasmic FlnA are a hallmark of metastatic prostate cancer supports the hypothesis that AR/FlnA complex detected upon androgen stimulation in cytoplasm of embryonic fibroblasts might be recapitulated during cancer progression and invasiveness." (PMID 21359179, 2011). "The higher affinity of TBECH-β to LNCaP AR and the frequency of the T877A mutation suggest that these compounds are active in a large proportion of prostate tumors and that they may contribute to the etiology of prostate cancer." (PMID 20049203, 2009). "High levels of AR are associated with increased proliferation, markers of aggressive disease and are predictive of decreased biochemical recurrence-free survival independently, confirming the role of AR in tumor growth and progression in hormonally naive prostate cancer." (PMID 15888205, 2005). "Our research demonstrated that KRAS has minimal influence during the AR-dependent stages of prostate cancer but significantly activates cancer cells when AR signaling is suppressed." (PMID 42069672, 2026). "Further investigation revealed that AR inhibition modifies fibroblast growth factor receptor expression in prostate cancer cells." (PMID 42069672, 2026). "Although PARP7i and AHRa can inhibit growth of both androgen receptor (AR)–positive prostate cancer cells and estrogen receptor (ER)–positive breast cancer cells, not all responsive cell lines were hormone receptor positive." (PMID 41295982, 2026).
prostate carcinoma (continued). "A pan-KRAS inhibitor effectively suppressed AR-independent prostate cancer cells by disrupting KRAS-mediated cell survival signaling." (PMID 42069672, 2026). "Developing novel agents targeting AR-independent oncogenes is critical to address this challenge, particularly for advanced castration-resistant prostate cancer." (PMID 41492471, 2026). "Resistance to androgen receptor inhibitors remains a primary challenge in prostate cancer treatment, yet identifying synergistic co-therapies is hindered by immense combinatorial search spaces and the limited interpretability of predictive computation models." (PMID 41659618, 2026). "Despite the tumor-suppressive role of lactoferrin established in other malignancies, we reveal its paradoxical oncogenic function in prostate cancer through an androgen receptor (AR)-LF-ferroptosis axis." (PMID 41945871, 2026). "More recently, we also demonstrated that AR directly represses MHC class I expression in prostate cancer, uncovering a tumor-intrinsic mechanism of an oncogene driving tumorigenesis while promoting immune evasion." (PMID 41486951, 2026). "Prostate cancer (PCa) progression is critically driven by androgen receptor (AR) signaling, which integrates hormonal cues with metabolic programs supporting tumor growth, survival, and therapy resistance." (PMID 41898513, 2026). "Strikingly, DALTAC-1 exhibits exquisite lineage selectivity, displaying potent activity in AR-positive prostate cancer cells and patient-derived organoids while sparing AR-negative or non-prostate lineages." (PMID 42094447, 2026). "The progression of prostate cancer to castration-resistant disease (CRPC) remains a clinical challenge in which oxidative stress intersects with the PI3K/AKT-androgen receptor (AR) axis." (PMID 41897538, 2026). "Patients with prostate cancer taking an androgen receptor signaling inhibitor (ARSI) for more than 2 yr experienced more fatigue, pain, and hormonal treatment–related symptoms." (PMID 41551331, 2026). "Prostate cancer (PCa) remains one of the most common malignant tumors among men worldwide, typically relying on the androgen receptor (AR) signaling pathway." (PMID 41639515, 2026). "Silencing TOPK sensitizes prostate cancer cells to androgen receptor-targeted therapies, demonstrating its role in ARv7 regulation." (PMID 41362722, 2026). "HDAC2 knockdown also abolished DHT repression of IKBKE in LNCaP cells, a different AR prostate cancer cell line." (PMID 41542764, 2026). "Targeting the androgen receptor (AR) signaling axis is the main therapeutic focus in the management of advanced prostate cancer (PCa)." (PMID 41531507, 2026). "Knockdown of CAND1 in prostate cancer cells reduced the expression of AR and ARv7 target genes, supporting its role as a coactivator." (PMID 42133602, 2026). "When androgen receptor (AR) signaling is suppressed, prostate cancer progression is inhibited; however, many patients eventually relapse, developing castration-resistant prostate cancer (CRPC)." (PMID 42069672, 2026). "In sum, this work advances our understanding of AR isoform actions and identifies additional potential therapeutic targets for castration-resistant prostate cancer." (PMID 42133602, 2026). "Enzalutamide (ENZ) and apalutamide (APA) are two second-generation androgen receptor inhibitors (SGARIs) that have been primarily used in the treatment of prostate cancer." (PMID 41823821, 2026). "The PI3K–Akt axis and androgen receptor signaling interact extensively during prostate cancer progression, influencing cell proliferation, survival, and metabolic adaptation." (PMID 41598250, 2026). "The androgen receptor (AR) is a key transcription factor in prostate cancer (PCa), whose enhanced and altered functions are known drivers of cancer progression." (PMID 42213546, 2026). "The initial effectiveness of ADT in prostate cancer patients is based on its ability to target the dependency of hormone sensitive prostate cancer (HSPC) to the AR activity." (PMID 39853587, 2026).
prostate carcinoma (continued). "We inferred AR activity using a network-based approach across bulk RNA sequencing [RNA-seq; The Cancer Genome Atlas (TCGA)], single-cell RNA-seq (prostate cancer meta-atlas), and immunotherapy cohorts." (PMID 41486951, 2026). "Single-cell analysis confirmed that tumor-intrinsic AR activity inversely correlates with immune infiltration in prostate cancer." (PMID 41486951, 2026). "Background/Objectives: The androgen receptor (AR)-driven transcriptional program plays a pivotal role in the development and progression of prostate cancer." (PMID 42194995, 2026). "Background/Objectives: Advanced prostate cancer (PCa) evolves through adaptive mechanisms that sustain tumor growth despite the suppression of androgen receptor (AR) signaling." (PMID 42122259, 2026). "Knocking down UHRF1 led to increased AR expression and enhanced the activity of canonical AR signaling pathway in prostate cancer cells." (PMID 41760602, 2026). "Results showed that the IC50 values of Q199, XDD60, and A79 were comparable to or even lower than those of enzalutamide, particularly in AR-inactive prostate cancer cell models." (PMID 41492471, 2026). "In prostate cancer, TOPK induces androgen receptor splice variant ARv7 expression, promoting androgen independence." (PMID 41362722, 2026). "Background/Objectives: Combinations of PARP inhibitors (PARPi) and androgen receptor pathway inhibitors (ARPi) have led to clinical success in treating advanced prostate cancer." (PMID 42193276, 2026). "The promotion of radioresistance by AKR1C3 in both AR-positive and AR-negative prostate cancer cells was further validated through in vivo and in vitro experiments." (PMID 41912503, 2026). "Docetaxel upregulates CLEC2D via the androgen receptor, reducing NK cell immunotherapy efficacy in castration-resistant prostate cancer." (PMID 40938562, 2026). "In prostate cancer (PCa), CAFs promote resistance to androgen receptor pathway inhibitor therapy, chemotherapy, and radiotherapy, emphasizing their potential value as therapeutic targets." (PMID 41684004, 2026). "Despite these findings, miR-16 is still commonly used as an endogenous qPCR normalizer, even though PCa cell studies show marked down-regulation of miR-16-5p and functional targeting of AR and EGFR, both closely linked to prostate cancer biology." (PMID 41598250, 2026). "To further evaluate the anti-tumor efficacy of these compounds, we determined their IC50 values in prostate cancer cells and compared them to enzalutamide, a widely used AR antagonist." (PMID 41492471, 2026). "This suggests that the immune-modulatory effects of AR inhibition are not limited to prostate cancer but extend to other tumor types." (PMID 41486951, 2026). "In prostate cancer cell lines, several AR regulators have been identified, including GATA2, HOXB13, FOXA1, and TFAP2C." (PMID 41596366, 2026). "Advances in single-cell and epigenomic profiling are poised to delineate further the heterogeneity and dynamics of AR cistrome remodeling in treatment-refractory prostate cancer." (PMID 41602415, 2026). "Because prostate cancer proliferates in an androgen-dependent manner, various inhibitors of androgen production and antagonists of the androgen receptor (AR) are used as therapeutic agents." (PMID 41752098, 2026). "This work defines lactoferrin as: (i) an AR-regulated ferroptosis suppressor, (ii) a regulator of prostate cancer's "iron addiction," and (iii) a candidate target for therapeutic exploitation of iron-metabolic vulnerability." (PMID 41945871, 2026). "Prostate cancer is dependent upon the androgen receptor (AR), the activity of which is modified by cofactors that either enhance or repress its activity, often in a context-dependent manner." (PMID 41651986, 2026).